APPL2 (adaptor protein, phosphotyrosine interacting with PH domain and leucine zipper 2)
Diseases named in the same sentence as APPL2 in open-access papers:
APPL2 is named in the same sentence as 31 diseases in open-access papers, as found by Europe PMC text mining. Sharing a sentence is not in itself a finding about the gene and the disease. The quoted sentences say what the papers report.
Obesity (6 papers, 2012 to 2024). Accumulation of substantial excess body fat. "A significant association of APPL2 genetic variation with overweight and obesity has been also found." (PMID 23977033, 2013). "Previous studies have demonstrated a significant association between APPL1 gene variants and body fat distribution in T2DM and a significant association of APPL2 genetic variation with overweight and obesity." (PMID 23977033, 2013). "Our data suggest that genetic variations in APPL2 are associated with overweight and obesity in the Chinese subjects with normal glucose tolerance." (PMID 22462604, 2012). "The mechanisms underlying the association between APPL2 and obesity are still unclear, and need to be further illuminated by functional studies." (PMID 22462604, 2012). "This study suggests that genetic variations in APPL2 are associated with overweight and obesity in Chinese population with normal glucose tolerance." (PMID 22462604, 2012). "APPL2 expression has been related to adiponectin and thus to obesity, insulin metabolism, and diabetes." (PMID 34930449, 2021). "We further investigated the effects of these SNPs at APPL2 on obesity-related measures, including BMI, waist circumference, hip circumference and WHR in all participants." (PMID 22462604, 2012). "Other noteworthy genes in our candidate list were APPL2, an adiponectin receptor associated with overweight and obesity in a Chinese population, DOCK5, a susceptibility gene for severe obesity, and SLC30A8, a zinc efflux transporter implicated in type 2 diabetes and obesity in Asians." (PMID 38355434, 2024). "In the present study, we tested five SNPs in APPL2 and identified two novel risk-conferring SNPs, rs2272495 and rs1107756, for overweight and obesity in non-diabetic individuals." (PMID 22462604, 2012). "Consistent with this presumption, our study found an association of APPL2 with overweight/obesity in non-diabetic individuals of Han Chinese ancestry, with rs2272495 C allele and rs1107756 T allele conferring a higher risk of being overweight and obese." (PMID 22462604, 2012). "In the current study, we aimed to test the impacts of APPL2 genetic variants on obesity in a Chinese population with normal glucose tolerance." (PMID 22462604, 2012). "Moreover, it was observed that key downstream regulatory molecules associated with adiponectin signaling, such as APPL1 and APPL2, are altered in endometria from women with obesity and IR, with or without PCOS." (PMID 35409282, 2022). "Therefore, we investigated the association of APPL2 with obesity and obesity-related quantitative traits in a Chinese non-diabetic population." (PMID 22462604, 2012).
depression (2 papers, 2019 to 2024). "BA also modulated APPL2-mediated glucocorticoid receptor hyperactivity and reversed corticosterone-induced depression-like behaviors." (PMID 31241715, 2019).
glioma (2 papers, 2013 to 2016). A benign or malignant brain and spinal cord tumor that arises from glial cells (astrocytes, oligodendrocytes, ependymal cells). "APPL1 and APPL2 have been linked to cell survival in vertebrate development and in human glioma cells." (PMID 26583432, 2016). "In support of this notion, the loss of glioma cell survival upon APPL2 knockdown can be rescued either by an excess of netrin‐1, the prosurvival ligand of UNC5B or by simultaneous silencing of HRK." (PMID 22989406, 2013). "Silencing of APPL2 leads to reduced viability of glioma cell lines, their decreased transformation abilities and impaired growth in vivo as xenografts." (PMID 22989406, 2013). "Cumulatively, these findings argue that depletion of APPL2 reduces the transformation abilities of glioma cells." (PMID 22989406, 2013). "In summary, we demonstrated that in both glioma cell lines knockdown of APPL2 decreases cell viability and induces activation of caspases followed by apoptotic cell death." (PMID 22989406, 2013). "The silencing of APPL2 expression by small interfering RNAs (siRNAs) in glioma cells markedly reduces cell survival under conditions of low growth factor availability and enhances apoptosis (measured by executor caspase activity)." (PMID 22989406, 2013). "In a model of two glioma cell lines, we demonstrated that silencing of APPL2 expression decreased their viability, apoptosis resistance and transformation abilities." (PMID 22989406, 2013). "To unravel the molecular mechanism responsible for the modulation of glioma cell survival and apoptosis by APPL2, we first examined the pattern of cellular signaling upon knockdown of APPL2 in LN229 and U87MG cells under conditions of low serum availability." (PMID 22989406, 2013). "In this study, we demonstrate that APPL2, an adapter protein with known endocytic functions, is upregulated in 40% cases of glioblastoma multiforme, the most common and aggressive cancer of the central nervous system." (PMID 22989406, 2013). "We therefore concluded that the signaling pathways of the dependence receptors might be functional in both glioma cell lines and UNC5B can be potentially responsible for the loss of their survival upon silencing of APPL2 expression." (PMID 22989406, 2013). "To test whether long‐term silencing of APPL2 expression can affect glioma cell growth we performed experiments with a stringent anchorage‐independent growth assay." (PMID 22989406, 2013). "We show that modulation of APPL2 level in glioma cells changes the expression of genes responsible for cell death induction, HRK and UNC5B, suggesting one possible molecular mechanism by which APPL2 may enhance tumor cell growth and apoptosis resistance." (PMID 22989406, 2013). "We selected two glioma cell lines, LN229 and U87MG with medium and high endogenous APPL2 protein levels, respectively (comparing to the panel of different cancer cell lines)." (PMID 22989406, 2013). "Instead, silencing of APPL2 expression had no obvious effect on the viability of mouse embryonic fibroblasts under normal culture conditions, similarly to our results in glioma LN229 cells." (PMID 22989406, 2013). "Cumulatively, these data argue that the endosomal localization of APPL2 is not required for its prosurvival activity and regulation of HRK expression in glioma cells." (PMID 22989406, 2013).
Autoimmunity (1 paper, 2013). The occurrence of an immune reaction against the organism's own cells or tissues. "We could detect expression of both APPL1 and APPL2 in small intestinal biopsies and a significantly lower expression of APPL2 was detected in the CD autoimmunity cases as compared to controls." (PMID 23936387, 2013).
bipolar disorder (1 paper, 2025). A disorder of the brain that causes unusual shifts in mood, energy, activity levels and the ability to carry out day-to-day tasks. "Detected in G2S but not in GTEx, these data provide the first evidence associating GReX of APPL2 with risk of bipolar disorder." (PMID 40166038, 2025).
brain tumors (1 paper, 2013). "A high level of APPL2 may contribute to the expansion of infiltrating tumor cells and favor some neoplastic properties of low‐grade brain tumors, since increase of its mRNA level was well noticeable in tumors of grade II and III." (PMID 22989406, 2013). "To test the potential involvement of APPL proteins in growth or progression of brain tumors, we first checked the level of APPL1 and APPL2 in protein extracts isolated from twenty five snap frozen human GBM samples." (PMID 22989406, 2013).
cardiomyopathy (1 paper, 2021). A disease of the heart muscle or myocardium proper. "Laboratory manipulations of APPL1 demonstrate protection against high-fat diet-induced cardiomyopathy in rodents and APPL2 is responsible for dietary regulation, cold-induced thermogenesis, and cold acclimation (uniprot.org)." (PMID 33686424, 2021).
celiac disease (1 paper, 2015). An autoimmune genetic disorder with an unknown pattern of inheritance that primarily affects the digestive tract. "Seven genes were down-regulated in the biopsies of celiac disease patients, among them NTS down-regulated 3.6 fold and the INSR, APPL2, ADCY9, GLS, HSPB1 and KIF13A 1.5-2.2 fold in the patient group (p < 0.001)." (PMID 26123480, 2015). "The gene APPL2 was down-regulated and NCALD up-regulated in both peripheral blood and the small intestine of celiac disease patients." (PMID 26123480, 2015).
glioblastoma multiforme (1 paper, 2013). "We report here that the level of APPL2 protein is increased in 40% cases of glioblastoma multiforme, when compared to non‐tumor brain tissue." (PMID 22989406, 2013). "Cumulatively, our data indicate that a high level of APPL2 protein might enhance glioblastoma growth by maintaining low expression level of genes responsible for cell death induction." (PMID 22989406, 2013).
Hepatic steatosis (1 paper, 2013). Steatosis is a term used to denote lipid accumulation within hepatocytes. "The impact of APPL1 and APPL2 SNPs on liver damage and hepatic steatosis severity has been also evaluated." (PMID 23977033, 2013).
Non-Alcoholic Fatty Liver Disease (1 paper, 2013). "The aim of our study will be the evaluation of a potential association between the APPL1 and APPL2 loci and the occurrence and progression of non alcoholic fatty liver disease (NAFLD)." (PMID 23977033, 2013).
osteosarcoma (1 paper, 2022). A usually aggressive malignant bone-forming mesenchymal neoplasm, predominantly affecting adolescents and young adults. "Expression of several other genes, including Appl2 was not significantly different in Cd44-positive and Cd44-negative osteosarcoma cells, although they were found to be differentially expressed in the tissue." (PMID 35955749, 2022).
prostate carcinoma (1 paper, 2016). A carcinoma that arises from epithelial cells of the prostate gland. "Taken together, these observations suggest that the endosomal proteins APPL1 and APPL2 are important for the nuclear trafficking of TβRI-ICD, which is regulated by TRAF6 and is linked to prostate cancer progression." (PMID 26583432, 2016). "In this report, we identify APPL1 as a TβRI- and PKCζ-associated protein and show that APPL1 and APPL2 are required for the nuclear translocation of TβRI-ICD, and thereby promote progression of prostate cancer cells." (PMID 26583432, 2016). "We also found that the TGFβ-induced invasion of cancer cells is dependent on APPL1 and APPL2 expression and that the APPL1 expression is increased in malignant prostate cancer tissues compared with normal prostate tissues." (PMID 26583432, 2016).
Sepsis (1 paper, 2014). Sepsis is defined as life-threatening organ dysfunction caused by a dysregulated host response to infection. "In the present study, the role of Appl2 in sepsis shock was investigated by using Appl2 knockout (KO) mice." (PMID 25328665, 2014).
steatosis (1 paper, 2013). Increased lipid within the cytoplasm of cells. "A logistic regression analysis revealed that individuals with at least one copy of the rs4640525 C allele and rs11112412 APPL2 A allele had a 2.17 (95% CI: 1.27–3.711; P = 0.004) and 1.96 (95% CI: 1.0008–3.83; P = 0.01) fold increased risk for severe steatosis respectively." (PMID 23977033, 2013).
tumor (4 papers, 2013 to 2025). "In summary, our data demonstrate for the first time an upregulation of APPL2 protein in human tumor samples." (PMID 22989406, 2013). "Generally, all cases of GBM with upregulated APPL2 levels detected by Western blotting also showed strong IHC anti‐APPL2 staining of tumor cells present both in the tumor center and in the surrounding brain tissue infiltrated by the tumor cells." (PMID 22989406, 2013). "The statistically significant reduction in tumor growth in vivo was observed for the cell pool with APPL2 silencing (APPL2‐sh) starting from day 23 post injection." (PMID 22989406, 2013). "To discriminate between these two possibilities we first measured the effect of APPL2 silencing on the viability of tumor cells." (PMID 22989406, 2013). "The mean fold change of APPL2 protein level was significantly increased in light tumor infiltrate and in tumor center groups (mean = 2.02 and 2.55, respectively)." (PMID 22989406, 2013). "Importantly, also in GBM samples containing light tumor infiltrate (the border region between non‐tumor tissue and tumor center) the level of APPL2 protein was significantly upregulated, although the number of investigated samples (7 cases) was small." (PMID 22989406, 2013). "Our results support a hypothesis that the high level of APPL2 protein in tumor cells may favor their resistance to apoptosis under limited growth factor availability." (PMID 22989406, 2013). "Upregulation of APPL2 protein levels in over 40% of human GBM samples could either actively contribute to tumor growth or progression, or be a passive consequence of the transformation process." (PMID 22989406, 2013). "Long‐term depletion of APPL2 by short hairpin RNAs (shRNAs), under regular growth factor availability, suppresses the cell transformation abilities, assessed by inhibited colony formation in soft agar and by reduced xenograft tumor growth in vivo." (PMID 22989406, 2013). "Semi‐quantitative Western blotting analysis using infrared imaging system revealed that APPL2 level was upregulated in twelve GBM samples (over 40% of cases), when compared to non‐neoplastic tissue (referred to as “non‐tumor”)." (PMID 22989406, 2013). "Likewise, the percentage of tumor involvement in the prostate gland showed a significant elevation in high expression group of ALDH1A (p = 0.038) and APPL2 (p = 0.054) compared to its counterpart group." (PMID 30397274, 2018). "Our results revealed that over 40% among 25 cases of human GBM appear to have a high level of APPL2 protein but not APPL1 when compared to non‐tumor tissue." (PMID 22989406, 2013). "It is possible that the negative effect of silencing of APPL2 expression on growth in soft agar, as well as on tumor growth in vivo, was exclusively dependent on the inhibition of cell proliferation or enhancement of apoptosis." (PMID 22989406, 2013). "This may implicate that the levels of Appl2 were influenced by tumor microenvironment, and we could not recapitulate the appropriate conditions in cell culture." (PMID 35955749, 2022). "Also the infiltrating gemistocytic tumor cells in case no 6 (large cells of irregular shape, white arrow) expressed high levels of APPL2." (PMID 22989406, 2013). "Analysis of the specimens from non‐tumor tissue revealed a population of cells (resembling normal brain cells, white arrow in case no 3) with APPL2 present both in the nucleus and in the cytoplasm, as well as a population of glial cells completely lacking anti‐APPL2 staining (yellow arrows)." (PMID 22989406, 2013). "In the infiltrating tumor cells present in GBM samples (cases no 1 and 2) the cell protrusions and nuclei were strongly stained with anti‐APPL2." (PMID 22989406, 2013).
cancer (2 papers, 2013 to 2016). A tumor composed of atypical neoplastic, often pleomorphic cells that invade other tissues. "Quantitative real-time polymerase chain reaction (qRT-PCR) analysis showed that transcription of the cancer-associated matrix metalloprotease 2 (MMP2) and MMP9 decreased after silencing of APPL1 and APPL2." (PMID 26583432, 2016). "Nuclear TβRI-ICD has been found to promote the invasion of various cancer cells and as APPL proteins was found to be crucial for its nuclear translocation, we investigated the role of APPL1 and APPL2 in TGFβ-induced invasiveness in cancer cells." (PMID 26583432, 2016). "The functional importance of nuclear TβRI-ICD is supported here by the finding that TGFβ-induced cancer cell invasion was suppressed after knockdown of APPL1 and APPL2." (PMID 26583432, 2016).
APPL2 also shares sentences with these, for which no sentence is quoted: anaplastic astrocytoma (1 paper); Anxiety (1); breast carcinoma (1); colorectal cancer (1); diabetes (1); gallbladder cancer (1); gastric cancer (1); melanoma (1); metabolic disease (1); oligoastrocytoma (1); oligodendroglioma (1); pancreatic cancer (1); sarcoma (1); type 2 diabetes (1).